CD320 (CD320 molecule)
Description:
Receptor for transcobalamin saturated with cobalamin (TCbl). Plays an important role in cobalamin uptake. Plasma membrane protein that is expressed on follicular dendritic cells (FDC) and mediates interaction with germinal center B cells. Functions as costimulator to promote B cell responses to antigenic stimuli; promotes B cell differentiation and proliferation. Germinal center-B (GC-B) cells differentiate into memory B-cells and plasma cells (PC) through interaction with T-cells and follicular dendritic cells (FDC). CD320 augments the proliferation of PC precursors generated by IL-10.
Synonyms: TCblR; 8D6A; 8D6; TCN2R; sCD320; TCII-R
Tractability: Small molecule: a structure with a bound ligand is known. Antibody: UniProt places it where antibodies can reach, with high confidence; its Gene Ontology location is reachable by antibodies, with high confidence; UniProt predicts a signal peptide or a membrane-spanning region. PROTAC: ubiquitination databases record sites on it.
Gene: Protein-coding gene on chromosome 19 (8,302,126 to 8,308,366, reverse strand). Ensembl gene ENSG00000167775.
Subcellular location: Cell membrane
Subcellular location (Human Protein Atlas): Vesicles
Pathways (Reactome):
Disease: Defective CD320 causes MMATC
Metabolism: Transport of RCbl within the body
Gene Ontology:
Molecular function: calcium ion binding; cargo receptor activity; cobalamin binding; protein binding
Biological process: B cell costimulation; cobalamin transport; positive regulation of B cell proliferation; vesicle-mediated transport
Cellular component: endoplasmic reticulum; membrane; plasma membrane
Genetic constraint (gnomAD): Loss-of-function variants: 16 observed, 16.3 expected, observed/expected ratio (o/e) 0.98, 90% interval 0.66 to 1.49. The synonymous counts are far from expectation, so gnomAD's model fits this gene poorly and the ratio says little. Missense variants: 380 observed, 329.81 expected, observed/expected ratio (o/e) 1.15, 90% interval 1.06 to 1.25. Synonymous variants: 185 observed, 148.6 expected, observed/expected ratio (o/e) 1.24, 90% interval 1.1 to 1.41.
Gene-disease validity (ClinGen):
ClinGen rates the evidence that CD320 causes each of these diseases.
methylmalonic acidemia due to transcobalamin receptor defect (autosomal recessive): Definitive.
Homologues: Orthologues: chimpanzee CD320 (99% identical), macaque CD320 (83% identical), rat Ndufa7 (59% identical), mouse Cd320 (56% identical), rabbit CD320 (56% identical), guinea pig CD320 (52% identical), pig CD320 (52% identical), dog CD320 (50% identical). Paralogues in human: LDLRAD2 (15% identical).
Diseases named in the same sentence as CD320 in open-access papers:
CD320 is named in the same sentence as 46 diseases in open-access papers, as found by Europe PMC text mining. Sharing a sentence is not in itself a finding about the gene and the disease. The quoted sentences say what the papers report.
vitamin B12 deficiency (7 papers, 2012 to 2025). A disease characterized by low serum levels of vitamin B12, either inherited or acquired. "It was accompanied by worsening the disease by both CD320 genetic deletion and vitamin B12 deficiency." (PMID 39125597, 2024). "Knockout of the CD320 gene in the mouse is not lethal, although the brain concentration of B12 is >90% reduced, and metabolites associated with vitamin B12 deficiency are selectively increased in brain in the CD320 knockout mouse." (PMID 35745855, 2022). "One may conclude that vitamin B12 deficiency caused by CD320 disruption might be linked with an increased risk of neurodegenerative diseases; thus, its evaluation might be an interesting prognostic parameter." (PMID 39125597, 2024). "Vitamin B12 deficiency causes DNA hypomethylation in the TCblR/CD320-knockout mouse brain." (PMID 36833292, 2023). "Considering the role of vitamin B12 in recycling of folate and de novo methionine production, our hypothesis is that vitamin B12 deficiency in the brain causes global DNA hypomethylation in the TCblR/CD320 mouse." (PMID 22607050, 2012). "Our study suggests that the CD320 knockout mouse develops behavioral deficits associated with cobalamin deficiency and therefore could provide a model to understand the metabolic and genetic basis of neuro-pathologic changes due to cobalamin deficiency." (PMID 28545069, 2017).
Anxiety (3 papers, 2017 to 2025). Intense feelings of nervousness, tension, or panic often arise in response to interpersonal stresses. "Higher anxiety is a well-reported neurologic condition associated with Cbl deficiency in humans which is also observed in the TCblR/CD320 KO mouse." (PMID 28545069, 2017). "In summary, Cbl deficiency in the CNS of the TCblR/CD320 KO mouse produces anxiety and behavioral deficits." (PMID 28545069, 2017). "The knockout of CD320 in mice resulted in impaired peripheral sensation, demyelination, and other functional and structural changes of the central nervous system (anxiety, memory deficits)." (PMID 40565117, 2025). "Neurologic alterations such as anxiety, deficits in learning and memory, and changes in brain mass were obtained in a knockout mouse in which the transcobalamin receptor (TCblR) gene (CD320) was ablated." (PMID 38338046, 2024). "We tested the TCblR/CD320 KO mouse in behavioral tasks to assess anxiety, learning and memory, which are known to be impaired in humans with Cbl deficiency." (PMID 28545069, 2017).
hepatocellular carcinoma (3 papers, 2024 to 2025). A malignant tumor that arises from hepatocytes. "Finally, TIMER analysis demonstrated that the infiltration of six immune cell types was significantly associated with high expression levels of CD320 in hepatocellular carcinoma." (PMID 38955924, 2024). "However, the relationships between CD320 and immune cell infiltration levels remain unclear, with limited studies investigating the diagnostic and prognostic significance of CD320 in hepatocellular carcinoma." (PMID 38955924, 2024). "Two studies involving osteosarcoma and hepatocellular carcinoma showed that CD320 plays an important role in cancer progression and proliferation." (PMID 40565117, 2025). "To verify our findings in different cell types, we conducted similar experiments on CD320 in human hepatoma HepG2 cells." (PMID 39551142, 2024). "We used various databases, including the TIMER, GEPIA, UALCAN and TCGA databases to investigate the expression levels of CD320 in hepatocellular carcinoma." (PMID 38955924, 2024). "Subsequently, we analyzed the prognosis of hepatocellular carcinoma patients with different expression levels of CD320." (PMID 38955924, 2024). "Finally, the functions of CD320 in hepatocellular carcinoma were also confirmed via relevant cell experiments and angiogenesis assays." (PMID 38955924, 2024). "Herein, we demonstrated that CD320 may play an important role in angiogenesis in hepatocellular carcinoma." (PMID 38955924, 2024). "Increased expression of CD320 was also correlated with a poor prognosis in patients with hepatocellular carcinoma, which suggested that CD320 may be a potential prognostic marker." (PMID 38955924, 2024). "Another study identified CD320 as an early biomarker of hepatocellular carcinoma (HCC)." (PMID 40565117, 2025). "In this work, we studied CD320 expression in transfected human embryonic kidney (HEK) 293 and hepatoma HepG2 cells." (PMID 39551142, 2024).
methylmalonic acidemia (3 papers, 2022 to 2025). A genetically heterogenous inherited disorder characterized by abnormalities in the metabolism of lipids and proteins. "NGS analysis was also critical in patient 086 who carried two CD320 gene (transcobalamin receptor) mutations and was affected by transient methylmalonic acidemia, TCblR type." (PMID 39856690, 2025). "One newborn with methylmalonic acidemia had two variants in the transcobalamin receptor gene (CD320) identified by the gene panel." (PMID 35225935, 2022). "Mutations in CD320 (transcobalamin receptor), involved in cobalamin import into cells, can also result in isolated methylmalonic acidemia." (PMID 35736461, 2022).
osteosarcoma (2 papers, 2024 to 2025). A usually aggressive malignant bone-forming mesenchymal neoplasm, predominantly affecting adolescents and young adults. "The study investigating the role of the tumor microenvironment in highly invasive osteosarcoma identified a high expression of CD320 and MAF genes in tumor infiltrating regulatory T cells (Tregs)." (PMID 40565117, 2025). "Upregulated expression of CD320 was also observed for osteosarcoma tissue compared to adjacent normal tissues." (PMID 40565117, 2025). "Therefore, similarly to HCC and osteosarcoma, CD320 might serve as a good prognostic marker and potential therapeutic target for adrenocortical carcinoma." (PMID 40565117, 2025).
acute pancreatitis (1 paper, 2024). An acute inflammatory process that leads to necrosis of the pancreatic parenchyma. "The phenotypes are consistent with reduced VB12 in pancreatic tissues in wild‐type mice and CD320‐ablation mice after induction of acute pancreatitis." (PMID 39415850, 2024). "As expected, the ATP treatment greatly reduced the pancreatic histopathological changes of acute pancreatitis in CD320‐ablation mouse models." (PMID 39415850, 2024). "In CD320‐ablation mice, acute pancreatitis induced with L‐Arg produced much severer pancreatic histopathological changes." (PMID 39415850, 2024). "We subjected GSH into the CD320‐ablation mice and induced acute pancreatitis by CER." (PMID 39415850, 2024). "In contrast, the serum lipase levels and the MPO+ neutrophil infiltration in pancreatic tissues did not change after ATP treatment in the CD320‐ablation mouse models with CER‐induced acute pancreatitis." (PMID 39415850, 2024). "The transcobalamin receptor (TCblR)/CD320 gene ablation that decreased cellular VB12 uptake and ATP production in pancreatic tissues promoted necrosis, resulting in much severe pathological changes of induced acute pancreatitis in mice." (PMID 39415850, 2024). "The CD320‐ablation greatly increased the levels of amylase and lipase in serum and CD3+ T lymphocyte infiltration, as well as the formation of ductal tubular complexes in the pancreas in mice with L‐Arg‐induced acute pancreatitis." (PMID 39415850, 2024). "After administering CER in wild‐type and CD320‐ablation mice, the level of VB12 in serum and pancreatic tissues significantly decreased in wild‐type mice, but not in CD320‐ablation mice, which is consistent with the L‐Arg‐induced acute pancreatitis models." (PMID 39415850, 2024).
adrenocortical carcinoma (1 paper, 2025). "Based on data retrieved from Gene Expression Profiling Interactive Analysis 2 (GEPIA2) database, the high CD320 expression in patients with adrenocortical carcinoma is associated with poorer overall and disease-free survival." (PMID 40565117, 2025).
Ataxia (1 paper, 2025). Ataxia refers to impaired coordination of voluntary muscle movement. "Moreover, analysis of serum and cerebrospinal fluid (CSF) of patients with tremor, ataxia, and scanning speech revealed the presence of patient-derived anti-CD320 antibodies in the patient samples, but not in the majority of healthy control samples." (PMID 40565117, 2025).
colorectal cancer (1 paper, 2024). A primary or metastatic malignant neoplasm that affects the colon or rectum. "Numerous cellular clusters across many solid tumors revealed differential expression of CD320 including stomach adenocarcinoma (STAD), colorectal cancer (CRC), Merkel cell carcinoma (MCC), NSCLC, ICC, and SKCM, among others." (PMID 39493449, 2024).
experimental autoimmune encephalomyelitis (1 paper, 2025). An autoimmune demyelinating disease of the central nervous system that is produced experimentally in animals by the injection of homogenized brain or spinal cord in Freund's adjuvant. "Downregulation of CD320 and B12 deficiency worsen anti-inflammatory responses in experimental autoimmune encephalomyelitis, and B12 deficiency is strongly linked to various peripheral and optic neuropathies and neurodegenerative diseases." (PMID 40345183, 2025).
gastric cancer (1 paper, 2025). A primary or metastatic malignant neoplasm involving the stomach. "Additionally, B12-conjugated PLGA-PEG nanoparticles (PLGA-PEG-VB12 NPs) effectively delivered microRNAs-532-3p to CD320-overexpressing gastric cancer cells, significantly reducing the expression of the apoptosis repressor ARC." (PMID 40507930, 2025).
glioma (1 paper, 2024). A benign or malignant brain and spinal cord tumor that arises from glial cells (astrocytes, oligodendrocytes, ependymal cells). "Serum MGMT expression and CPTAC notably overlapped with respect to CTSA (upregulated in glioma and associated with immune infiltration), MTFHD1 (one-carbon metabolism association in GBM), and CD320 (implicated in a cobalmin-mediated metabolism)." (PMID 38612892, 2024).
human papillomavirus infection (1 paper, 2024). "Furthermore, pathway analysis showed that CD320 was strongly associated with the PI3K-Akt signaling pathway, human papillomavirus infection, the MAPK signaling pathway, and Salmonella infection." (PMID 38955924, 2024).
Huntington disease (1 paper, 2022). Huntington disease (HD) is a rare neurodegenerative disorder of the central nervous system characterized by unwanted choreatic movements, behavioral and psychiatric disturbances and dementia. "Other genes highlighted by this study include CD320, which was reported to be associated with Huntington’s disease in a previous EWAS; USP43, which was shown to have DNAm levels associated with progressive supranuclear palsy; APBA2, which was reported in an EWAS of Parkinson’s disease (PD)." (PMID 36359320, 2022).
hyperhomocysteinemia (1 paper, 2023). A serious metabolic condition caused by mutations in the MTHFR gene, medications, or nutritional deficiency. "For instance, there is a possible association between variants in the RTEL1 gene and stroke risk in the Chinese population while CD320 (transcobalamin 2 receptor) is known to be associated with hyperhomocysteinemia, which is a risk factor for cardiovascular disease." (PMID 37098010, 2023).
liver cancer (1 paper, 2022). An epithelial or non-epithelial malignant neoplasm that arises from the liver. "This is consistent with our research findings and indicates that CD320-targeted immunotherapy may become a novel targeted immunotherapy approach for liver cancer." (PMID 36401409, 2022).
lymphoma (1 paper, 2017). A malignant (clonal) proliferation of B- lymphocytes or T- lymphocytes which involves the lymph nodes, bone marrow and/or extranodal sites. "Furthermore, anti-CD320 antibodies inhibit the proliferation of the lymphoma cell line L3055." (PMID 29228738, 2017).
multiple myeloma (1 paper, 2021). "Among all dysregulated immune-related mRNAs, AEN, CD320, FABP5, and GPI were risk factors for multiple myeloma, while CXCL12, IGKC, NOD2, VCAM1, and WNT5A were protective factors for multiple myeloma." (PMID 34249967, 2021).
osteoporosis (1 paper, 2020). A condition of reduced bone mass, with decreased cortical thickness and a decrease in the number and size of the trabeculae of cancellous bone (but normal chemical composition), resulting in increased fracture incidence. "Among them, the combination of CD320 C-TCN2 T-SLC19A1 G-SLC19A2 T showed the strongest association with osteoporosis risk." (PMID 32498429, 2020). "In the present study, we explored possible associations between SNPs located in the 3 ́–UTR of the CD320, TCN2, SLC19A1, and SLC19A2 genes and osteoporosis and OVCFs in 301 postmenopausal women." (PMID 32498429, 2020). "Our findings suggest that SNPs in the miRNA binding site within the 3’–UTR of the CD320 gene may contribute to osteoporosis and OVCF occurrences in some individuals with high homocysteine level." (PMID 32498429, 2020). "Our findings suggest that SNPs within the CD320 gene in 3 ́-UTR may contribute to osteoporosis and OVCF occurrences in some individuals." (PMID 32498429, 2020). "The incidence of osteoporosis was significantly higher for genotype CD320 rs9426 CT+TT than genotype CC both in patients ≥69 years of age (AOR 2.399, CI 1.101–5.226) and in patients with high homocysteine concentrations (homocysteine > 12.68 μmol/L) (AOR 5.019, CI 1.533–16.430, p < 0.05)." (PMID 32498429, 2020). "Furthermore, specific allele combinations of CD320, TCN2, SLC19A1, and SLC19A2 may contribute to increased susceptibility to osteoporosis and OVCF." (PMID 32498429, 2020). "There was a significantly higher incidence of both osteoporosis (AOR 5.019; 95% CI, 1.533–16.430, p < 0.05) and OVCF (AOR, 5.760; 95% CI, 1.480–22.417, p < 0.05) in individuals with genotype CD320 CT+TT and high homocysteine concentrations." (PMID 32498429, 2020). "Overall, the results of the present study indicate that the incidence of osteoporosis and OVCF is significantly increased in a subset of patients who are carrying genotype CD320 CT+TT and have high homocysteine levels." (PMID 32498429, 2020). "Our analyses therefore suggest that the allelic combinations of CD320, TCN2, SLC19A1, and SLC19A2 genes could play a role in the pathogenesis of osteoporosis and OVCF." (PMID 32498429, 2020). "The genotype and allele frequencies of the CD320 rs9426C>T, TCN2 rs10418 C>T, SLC19A1 rs1051296 G>T, and SLC19A2 rs16862199 C>T SNPs were compared between control subjects and osteoporosis patients with or without OVCF." (PMID 32498429, 2020). "Allele combination analysis revealed that two combinations, namely CD320 C-TCN2 T-SLC19A1 T-SLC19A2 C (OR, 3.244; 95% CI, 1.478–7.120, p < 0.05) and CD320 T-TCN2 C-SLC19A1 G-SLC19A2 C (OR, 2.287; 95% CI, 1.094–4.782, p < 0.05), were significantly more frequent among the osteoporosis group." (PMID 32498429, 2020).
thrombophilia (1 paper, 2023). A condition characterized by an abnormally high level of thrombi. "CD320, RTEL1, UCP2, APOA5 and PROZ participate in healthy-specific or disease-specific subnetworks involving thrombophilia-annotated genes and are related to general thrombophilia mechanisms according to the literature." (PMID 37098010, 2023).
triple-negative breast carcinoma (1 paper, 2025). An invasive breast carcinoma which is negative for expression of estrogen receptor (ER), progesterone receptor (PR), and human epidermal growth factor receptor 2 (HER2). "Here we found that the vitamin B12 receptor, CD320, is significantly increased in cancer stem cells (CSCs) in models of triple-negative breast cancer." (PMID 40985010, 2025). "We found that expression of CD320 protein is increased (~2.3-fold) in sorted cultures of CSCs compared to nonCSCs in the human triple-negative breast cancer (TNBC) cell line MDA-MB-231-LM2 (‘231-LM2’)." (PMID 40985010, 2025).
viral infection (1 paper, 2024). "Ultimately, CD320 expression was also negatively associated with OS and RFS in patients without viral infection." (PMID 38955924, 2024).